CXCL12 (C-X-C motif chemokine ligand 12)
Diseases named in the same sentence as CXCL12 in open-access papers (continued):
Sharing a sentence is not in itself a finding about the gene and the disease.
glioblastoma (continued). "CXCL12 also plays a crucial role in tumor proliferation and invasion as well as in the metastasis of cancerous cells such as those of breast cancer or glioblastoma multiforme (GBM)." (PMID 32295255, 2020). "A sustained CXCL12 gradient created by a delivery system can be used, as a therapeutic approach, to control the migration of cancerous cells infiltrated in peri-tumoral tissues similar to those of glioblastoma multiforme (GBM)." (PMID 32295255, 2020). "In glioblastoma, stabilization of HIF-1α stimulates auto/paracrine SDF-1 (CXCL12)/CXCR4-mediated chemotaxis the programming of which strongly depends on electrosignaling as one key regulator of chemotaxis." (PMID 30930892, 2019). "Along those lines, the chemokine SDF-1 (stromal cell-derived factor-1, CXCL12) via its receptor CXCR4 stimulates migration of glioblastoma cells." (PMID 26893360, 2016). "In accordance with previous studies, we demonstrated that the CXCL12/CXCR4 axis plays a substantial role in regulating the proliferation, drug resistance, and neovascularization of glioblastoma." (PMID 23961808, 2013). "Introduction of LRRC4 into glioblastoma cells reduced CXCR4 expression, CXCL12-induced ERK and AKT phosphorylation and matrix metalloproteinase expression." (PMID 20376365, 2010). "Moreover, activation of the CXCL12/CXCR4 signalling pathway reportedly increases MMP-9 and VEGF expression in glioblastoma." (PMID 38594611, 2024). "For example, chemokine CXCL12 binds to both CXCR4 and CXCR7 in glioblastoma." (PMID 37771579, 2023). "In addition, the novel CXCR4 antagonist, PRX177561, has been proven to regulate the CXCL12/CXCR4 pathway in both in vitro and in vivo models of glioblastoma." (PMID 36980182, 2023). "More recently, it was found that ERK signal may be involved in the potential contribution of CXCL12/CXCR4 to survival of cancer cells and chemoresistance in glioblastoma." (PMID 38031087, 2023). "Additionally, endothelium-derived CXCL12 attracts MDSCs into the TME and contributes to its immunosuppressive characteristics (discussed under ‘Modulating the immune TME’), particularly in glioblastoma." (PMID 36568151, 2022). "Furthermore, in glioblastoma the inhibition of CXCR4 and CXCL12 by a miRNA cluster blocked tumor development in mice with cancer cells implanted into the striatum and decreased the expression of OCT4 and NANOG in vitro." (PMID 36118530, 2022). "The CXCL12—CXCR4 axis is extensively expressed in the normal brain and plays an important role in CNS development, but its participation in glioblastoma may be an example of tumor cells “hijacking” physiological processes in the CNS." (PMID 35269652, 2022). "Furthermore, CD133+ glioblastoma stem cells exhibited the ability to recruit hUCBMSCs, which can further promote tumor growth in vivo, via exosomes containing MCP-1/CCL2 and SDF-1/CXCL12." (PMID 33849537, 2021). "Despite ACKR3 being recognised as a CXCL12 scavenging receptor, the functional role of ACKR3 in glioblastoma is complex because it might regulate CXCL12 levels in the TME and concomitantly modulate CXCR4 signalling." (PMID 33803414, 2021). "The contribution of CXCL12 and its receptor CXCR4 in glioblastoma may be considered as an example of tumor cells “hijacking” of physiological processes in CNS." (PMID 34200145, 2021). "High levels of CXCR4/CXCL12 expression in PCNSL and in glioblastomas have been shown previously." (PMID 32239371, 2020). "Upregulated expression of CXCL12 and its receptor CXCR4 was observed in various types of malignant CNS tumors, including low-grade oligodendrogliomas, oligoastrocytomas, and astrogliomas as well as high-grade glioblastomas." (PMID 32456359, 2020). "We show that AurA contributes to glioblastoma cell survival, radio-resistance, self-renewal, and proliferation regardless of the exogenous stimulation with CXCL12." (PMID 30082913, 2019).
glioblastoma (continued). "Moreover, in glioblastoma cancer stem cells (GCSCs) and in alternatively polarized TAMs hypoxia stimulates VEGF and stromal cell-derived factor 1 (SDF-1, also known as CXCL12) production." (PMID 29584702, 2018). "Furthermore, CXCL12/SDF-1α induced a significant increase of DNA synthesis in primary human glioblastoma cell cultures and chemotaxis in a glioblastoma cell line." (PMID 24971349, 2014). "The in vitro invasiveness assay suggested that the CXCL12/CXCR4 pathway is not vital to the migration of RG2 glioblastoma." (PMID 23961808, 2013). "In this latter study, downregulation of IK1 expression using shRNA completely inhibited cell migration in response to the chemokine ligand CXCL12 in several glioblastoma cell lines and primary GBM cells, suggesting a possible role of IK1 in glioblastoma invasiveness." (PMID 20808839, 2010). "Moreover, CXCR4/CXCL12 signaling upregulates survival via the MED/ERK and PI3K/AKT pathways, giving rise to cell-cycle progression and EMT in multiple tumors, for example, in human sacral chondrosarcoma, in glioblastoma, and in hepatocellular carcinoma." (PMID 40142155, 2025). "This tropism may be related to the monocyte chemoattractant protein 1 (MCP-1)/CC motif chemokine ligand 2 (CCL2) and stromal cell-derived factor-1 (SDF-1)/CXC motif chemokine ligand 12 (CXCL12) chemokines, which mediate MSC migration to CD133+ glioblastoma cells in vitro." (PMID 35741334, 2022). "Adding OLA-PEG, a novel CXCL-12 inhibitor, to bevacizumab or B-20 (anti-VEGF agent) significantly improved the anti-tumor effect by reducing intratumoral CD68+ TAM accumulation and by increasing the survival of tumor-bearing mice in the orthotopic G12 human glioblastoma model." (PMID 34209679, 2021). "In vivo observations indicated that the role of the CXCL-12/CXCR4 axis in the local recurrence or invasiveness of glioblastoma may be vital in modulating the ability of glioblastoma cells to proliferate and induce angiogenesis, but not to migrate." (PMID 23961808, 2013). "However, in contrast to enrichment of CXCR4+ T cells in glioblastoma, the greater abundance of CXCR4 on these cells may reflect redundancy of this axis in tumour infiltration as ligation of CXCR4 by CXCL12 results in receptor internalisation and desensitisation." (PMID 35464424, 2022). "In contrast, glioblastoma tumour cells may be the main source of CCL2, CXCL10 and CXCL12 production in the tumour microenvironment given the elevated CCL2 detected in GNS cell culture supernatants and the minimal levels of CXCL10 and CXCL12 detected in dissociated tumour supernatants." (PMID 35464424, 2022). "Recent evidence supports the hypothesis human glioblastoma arises from neural stem cells in the subventricular zone (SVZ) though, in a xenograft model, GBM cells have been found to migrate from the tumor to SVZ which was reported to constitute a CXCL12-dependent radioresistant niche." (PMID 30813533, 2019). "The CXCL12/CXCR4 pathway regulates tumor cell proliferation, metastasis, angiogenesis and the tumor-microenvironment cross-talk in several solid tumors, including glioblastoma (GBM), the most common and fatal brain cancer." (PMID 27015814, 2016). "Consistently, upregulation of CXCL12 and downregulation of CXCR7 were observed in temozolomide-resistant glioblastoma U87MG, A172, and Pt#3 cells, without consistent change in CXCR4 expression." (PMID 38898023, 2024).
colorectal cancer (125 papers, 2007 to 2025). A primary or metastatic malignant neoplasm that affects the colon or rectum. "It has been reported that CXCL12/CXCR7 promotes lung metastasis of colorectal cancer (CRC); however, the underlying mechanism remains poorly understood." (PMID 35443745, 2022). "The C-X-C motif chemokine ligand 12 (CXCL12) promotes cancer progression in several models, including colorectal cancer, facilitates cancer metastasis, and is associated with poor prognoses in colorectal cancer patients." (PMID 36232920, 2022). "Is there a correlation between autocrine IL-1α and paracrine CXCL12 in colorectal cancer, and does this association affect liver metastasis of colorectal cancer?" (PMID 34930323, 2021). "Epidemiologic studies have shown that high levels of CXCL12 are associated with increased risk for several common cancers, including those of breast, gastric cancer, hepatocellular carcinoma and colorectal cancers." (PMID 31500630, 2019). "Moreover, the colorectal cancer hallmark (CXCL12) is able to induce miR-125 upregulation and generate the chemotherapy drugs 5-FU resistance." (PMID 37190032, 2023). "For example, in colorectal cancer, where the role of CXCL12 expression and its association with the overall survival is controversial, our team showed that high expression of CXCL12 can increase the prognostic value of CD8 + T cell density in stage III disease." (PMID 37966614, 2023). "In contrast, in a murine model of colitis-associated colorectal cancer, miR-126 (which was downregulated in patients with colorectal cancer) reduced CXCL12 expression in intestinal epithelial cells functioning as a tumor suppressor by inhibiting the recruitment and function of macrophages." (PMID 36725964, 2023). "Further analysis showed that differentially expressed genes such as PPBP, CCL28, and CXCL12 are likely to be involved in the development of colorectal cancer and may be potential diagnostic and therapeutic targets." (PMID 32797167, 2020). "In phase II, we focused on five HIF-coding genes (HIF1A, HIF1B, HIF2A, HIF2B and HIF3A) and two hypoxia-inducible genes (LOX and CXCL12) and investigated the relationship of their SNPs (n = 77) with the risk of outcome in an additional colorectal cancer patient cohort (n = 535)." (PMID 25405996, 2014). "Liver-specific metastasis of colorectal cancer cells can also be explained by their expression of some chemokines and by responding of colorectal cancer cell-expressed receptors to specific homing signals from liver (CXCL12)." (PMID 40758205, 2025). "Activation of CXCL12/CXCR4 confers radioresistance of colorectal cancer cells by upregulating survivin expression." (PMID 38164179, 2024). "In colorectal cancer, CXCL12/CXCR4-mediated upregulation of miR-125b initiates a similar cascade to evade the effects of 5-fluorouracil." (PMID 38818409, 2024). "This transition results in immune suppression and the induction of EMT in colorectal cancer, thereby promoting the expression of CXCL12 in primary tumors." (PMID 38920657, 2024). "For example, CAF-derived CXCL12 accelerates colorectal cancer progression and induces cisplatin resistance in vivo by promoting the M2 polarization of macrophages." (PMID 38818409, 2024). "Significantly higher GREMLIN1, NOGGIN, and CXCL12 expression were detected in the Consensus Molecular Subtype 4 (CMS4) colorectal cancers, which are thought to arise from serrated polyps." (PMID 36326956, 2023). "A recent study suggested a role for exosomal miR-146a-5p and miR-155–5p promoting CXCL12-induced metastasis of ACKR3-expressing colorectal cancer cells." (PMID 36725964, 2023).
colorectal cancer (continued). "While studying CXCL12 expression in colorectal cancer, we found that the increased expression of CXCL12 was in the plasma membrane of the invasive front of residual LARC cells after nCRT in our preliminary examples." (PMID 34976180, 2022). "Similar observations were obtained for colorectal cancer, where the expression of CXCL12 and CXCR4 was higher in lung metastases than in the primary focus." (PMID 36012171, 2022). "CXCL12/CXCR7 biased signal has been reported to play crucial roles in multiple stages of colorectal cancer (CRC)." (PMID 36210463, 2022). "C-X-C motif chemokine receptor 7 (CXCR7) is a newly discovered atypical chemokine receptor that binds to C-X-C motif chemokine ligand 12 (CXCL12) with higher affinity than CXCR4 and is associated with the metastasis of colorectal cancer (CRC)." (PMID 35443745, 2022). "Some studies have demonstrated reverse expression between CXCR4 and CXCL12 in colorectal cancer 35, 36, and CXCR4 expression correlated with poor prognostic survival outcomes." (PMID 34976180, 2022). "Wendt el al found that CXCL12 was silenced by DNA hypermethylation in primary colorectal carcinomas as well as colorectal carcinoma-derived cell lines." (PMID 35429301, 2022). "IL-Ra can inhibit the tumor-promoting effect of CXCR4/CXCL12 signal in the microenvironment of colorectal cancer by antagonizing the secretion of IL-1α in colorectal cancer cells, and then inhibit the liver metastasis of colorectal cancer." (PMID 34930323, 2021). "The colorectal cancer cells proliferation were enhanced by CXCL12 in a concentration-dependent manner." (PMID 34930323, 2021). "The colorectal cancer cell-derived IL-1α and rIL-1α significantly promoted CXCL12 expression by fibroblasts, and this enhancing effect can be significantly inhibited by IL-1Ra (P < 0.01)." (PMID 34930323, 2021). "The aim of this study was to investigate the co-operative role of CXCR4/CXCL12 axis and IL-1Ra in metastatic processes mechanism by interactions between colorectal cancer cells and stromal cells in their microenvironment." (PMID 34930323, 2021). "After transfected with CXCR4 siRNA or co-cultured with fibroblasts, colorectal cancer cells were pretreated with different concentration of CXCL12 and incubated for 24 h, and then cell invasion were performed by Matrigel assay." (PMID 34930323, 2021). "CXCL12 can not only promote the proliferation of colorectal cancer cells, but also enhance the proliferation of vascular endothelial cells, which is positively correlated with the concentration of CXCL12." (PMID 34930323, 2021). "Our previous studies have shown that the protection of colorectal cancer cells from radiotherapy by CXCL12/CXCR4 is mediated by survivin in colorectal cancer." (PMID 34439306, 2021). "The promotion of invasive capability of colorectal cancer cells by CXCL12 were blocked by CXCR4 siRNA (*P < 0.01compared with control)." (PMID 34930323, 2021). "To confirm the interaction between colorectal cancer and stromal cell-derived CXCL12 in tumor microenvironment, we next examined the effect of CXCL12 on colorectal cancer cell invasiveness using invasion assay." (PMID 34930323, 2021). "The invasive capability of colorectal cancer cells were enhanced by CXCL12 in a dose-dependent manner, 100 ng/mL of CXCL12 was significantly promoted cancer cells invasiveness (*P < 0.01)." (PMID 34930323, 2021). "The CXCL12 protein, also termed SDF-1, has six alternatively spliced variants, and the SDF-1β and SDF-1γ variants are associated with tumor size in colorectal cancer." (PMID 34281234, 2021). "It has been proved that after colorectal cancer cells activate the CXCL12/CXCR4 axis, the miRNAs secreted by colorectal cancer cells can be absorbed by macrophages and transform macrophages to M2 phenotype by targeting PTEN." (PMID 34930323, 2021).
colorectal cancer (continued). "We performed a literature search in PubMed and Google Scholar including the terms “Cytokines”, “Chemokines”, “CXCL12“, “Colorectal Cancer”, and “Metastasis” that resulted in 82 and 250 hits, respectively, in the last 10 years." (PMID 34298991, 2021). "The CXCL12/CXCR4 axis also activates the EMT program in colorectal cancer, targeting the Wnt/β-catenin pathway, and in multiple carcinomas such as pancreatic cancer, ovarian cancer and non-small cell lung cancer (NSCLC)." (PMID 32708431, 2020). "Activation of CXCR4, a chemokine receptor specific for stromal-derived-factor-1 (SDF-1 also called CXCL12), is highlighted in the development and the metastasis of colorectal cancers." (PMID 31275425, 2019). "It is thought the CXCR4/CXCL12 axis is an important factor inducing liver metastasis in colorectal cancers." (PMID 31275425, 2019). "Liver metastasis is a very important characteristic of colorectal cancer, and it is believed that the CXCR4 expressed on the colorectal cancer cells responds to the CXCL12 released from liver which induced the directional metastasis." (PMID 31275425, 2019). "The other studies have shown that the expressions of CXCL12 and CXCR4 in colon cancer patients are associated with liver metastasis, recurrence rate and survival rate in colorectal cancer patients." (PMID 29305742, 2018). "A recent study reported that CXCL12 enables colorectal cancer stem cells to initiate transcription of Cd44 v6 through activating the canonical Wnt17." (PMID 29402989, 2018). "Wendt et al47 recently reported that the expression of CXCL12 in human colorectal carcinoma cells reduced orthotopic tumor formation and inhibited metastasis in severe combined immunodeficient mice." (PMID 30013305, 2018). "In the first phase, 49 SNPs from six hypoxia pathway genes (HIF1A, HIF1B, HIF2A, LOX, MIF and CXCL12) in 272 colorectal cancer patients were analyzed." (PMID 25405996, 2014). "Colorectal cancer cell adhesion to endothelium is a key event in tumor progression; CXCL12/SDF-1α treatment stimulates intercellular adhesion molecule-1 (ICAM-1) expression, thus promoting tumor cell adhesion." (PMID 24971349, 2014). "Due to the crucial role of HIF-1α and CXCR4/CXCL12 in the metastatic process of colorectal cancer, we determined CXCR4 and CXCR7 gene expression in human colon carcinomas and their modulation by hypoxia and HIF-1α in colon cancer cell lines." (PMID 24629239, 2014). "Previously, we had observed that re-expression of CXCL12 in colorectal cancer cells lead to increased anoikis, detachment based apoptosis." (PMID 24594697, 2014). "As regards to CXCL4L1, the product of the nonallelic variant gene of CXCL4, it has been shown to inhibit neovascularization and counterbalance angiogenic activity mediated by VEGF, CXCL8, and CXCL12 in esophageal and colorectal cancer." (PMID 24971349, 2014). "Taken together, these results indicate the potential of targeting HIF-1α and CXCR4/CXCL12 in colorectal cancer." (PMID 24629239, 2014). "Our aim was to study the significance of targeting HIF-1α and the CXCR4/CXCL12 axis in colorectal cancer to prevent the dissemination process in vitro." (PMID 24629239, 2014). "Interactions between CXCR4 and its ligand CXCL12 have been shown to be involved in cancer progression in colorectal cancer (CRC)." (PMID 21349176, 2011). "Subsequently, we used a novel CXCR7-specific antagonist CCX771 and an endogenous CXCR7 ligand (CXCL12) to investigate the role of CXCR7 in regulating CXCL12-mediated colorectal carcinoma cell proliferation, apoptosis and migration." (PMID 22180778, 2011). "Data herein delineate the molecular process by which CXCL12 re-expression regulates Bim and Mcl-1 to initiate anoikis in colorectal cancers." (PMID 20877573, 2010). "Repression of Bim protein levels by RNAi rescued anoikis resistance in CXCL12-expressing cells describing Bim as a critical physiological step for colorectal carcinoma anchorage-independent survival and tumor metastasis." (PMID 20877573, 2010).